C1QB (complement C1q B chain)
Diseases named in the same sentence as C1QB in open-access papers (continued):
Sharing a sentence is not in itself a finding about the gene and the disease.
cancer (23 papers, 2011 to 2025). A tumor composed of atypical neoplastic, often pleomorphic cells that invade other tissues. "The RSF model identified key predictive genes including OLFML2B, ACTB, and C1QB, and demonstrated broad applicability across multiple cancer types." (PMID 39925852, 2025). "The TIMER database was used to analyze the correlation between mRNA expression of APOE, BGN, BST2, and C1QB and infiltrating immune cells in cancer tissues." (PMID 39650066, 2024). "The dysregulation of C1QB in many malignant tumors makes it an attractive target for clinical research." (PMID 36313902, 2022). "In particular, C1QB expression was strikingly well-predicted in 17/28 different cancer datasets (R = 0.39 ± 0.15)." (PMID 32747659, 2020). "A variable expression status of C1QB has been reported in some malignant tumors." (PMID 36313902, 2022). "Further analysis using blood fractionation showed that CD45− and CD45+ populations were responsible for the altered expression levels of PLEK2 and C1QB, respectively, indicating the importance of analyzing whole blood cells for blood-based biomarker studies of cancer." (PMID 21698244, 2011). "Consistently, previous studies have shown that SPP1, APOE, C1QA, C1QB, and C1QC are significantly elevated in the plasma of patients with cancer." (PMID 37187751, 2023). "In the present study, we used the GEPIA database to conduct pan-cancer analysis on the transcription levels of C1QA, C1QB, and C1QC and screened out the cancer types with the differential expression of these three genes." (PMID 36110204, 2022). "In conclusion, the current study showed that C1QA, C1QB, and C1QC were highly expressed in a variety of cancers, especially in SKCM, which overexpressed these three complement components and predicted better survival prognosis." (PMID 36110204, 2022). "We then performed a survival analysis of these differentially expressed cancers using the TIMER database and found that in SKCM, the expression levels of C1QA, C1QB, and C1QC were significantly correlated with OS." (PMID 36110204, 2022). "Complement C1Q is composed of C1QA, C1QB, and C1QC and is involved in the occurrence and development of many malignant tumours." (PMID 36110204, 2022). "The expression of C1QA, C1QB, and C1QC genes was analyzed between different carcinoma and normal tissue counterparts using the Oncomine database." (PMID 31130944, 2019). "The C1QA, C1QB, and C1QC genes were either over-expressed, or downregulated depending on the type of carcinoma investigated, as compared to their normal tissue counterparts." (PMID 31130944, 2019). "The genes (PLEK2 and C1QB) identified in this study have not been well investigated in cancer biology." (PMID 21698244, 2011). "We also determined that TREM2+ TAMs highly expressed soluble factors such as SPP1, APOE, C1QA, C1QB, and C1QC, which suggested that this TREM2+ TAMs subset may be exocrine or paracrine for establishing the microflora critical for cancer cell invasion and the metastasis environment." (PMID 37187751, 2023). "In addition, cancer-cell-intrinsic inflammatory tumor subclusters also showed an upregulation of C1R (log2FC = 0.86), C1S (log2FC = 0.46), and C3 (log2FC = 0.48), while the corresponding macrophages showed an upregulation of C1q genes (C1QA, C1QB, C1QC)." (PMID 36973268, 2023).
infection (17 papers, 2012 to 2026). The state of being infected such as from the introduction of a foreign agent such as serum, vaccine, antigenic substance or organism. "RNA sequencing data revealed a distinct pattern of gene expression during infection: Cd209a expression decreased progressively, whereas C1qa and C1qb expression increased consistently." (PMID 40170749, 2025). "Our KEGG pathway enrichment analysis indicates that the up-regulated DEGs including C3, PLG, CFD, CR1, and C1QB are still enriched in complement and coagulation cascades, up to 24 h after infection." (PMID 31316336, 2019). "Additionally, the C1qb and C3ar1 genes were significantly upregulated in all infection groups except in Omicron-infected lungs at 3 dpi." (PMID 40416961, 2025). "Furthermore, expression of C1qb by DC can bind to apoptotic cells and facilitate their clearance, thus contributing to the overall resolution of an immune response following infection." (PMID 22984588, 2012). "Additionally, 46 genes encoding for secreted proteins may serve as markers in blood for the degree of protection (Cxcl9, Gp2, and Pla2g2d), intensity of infection (Retnla, Saa3, Il6, and Il1b), or adaptive recall responses (Ighg, C1qb)." (PMID 28243609, 2017). "Next, involvement of complement genes vital in phagocytosis (C1QA, C1QB, C1QC, C1R), which play a central role in immunity, response to infection, as well as synaptic pruning, further implicate the involvement of the immune system in ASD." (PMID 36590292, 2022). "Humoral immune response related GO terms such as humoral immune response was common to both, while B cell mediated immunity (C1QB, HLA-DRA, C1QC, FCERIG, CIQA, CLU) was uniquely in subclinical infection." (PMID 32012176, 2020). "Of particular interest, the expression of 6 genes (VSIG4, LAMP1, QPCT, C1QB, TNFSF13, and JUN) can be used to distinguish the transcriptomic signature of a dormant infection from an uninfected joint replacement highlighting the potential for these markers in diagnosing a dormant infection." (PMID 39563367, 2024). "Myeloid dendritic cells in dormant infections also showed notable differences in mRNA expression, affecting neutrophil recruitment (C1QA, C1QB, ITGAM), immune checkpoint regulation (IFITM2, IFITM3, CST7, THBS1), and T-cell response (VISIG4, V-set immunoglobulin domain containing 4)." (PMID 39563367, 2024). "Furthermore, a broad activation pattern of the complement system—encompassing both effector components (e.g., C2, C3, C8A, C9) and regulatory proteins (e.g., CFH, CFI, C1QB)—is consistent with prolonged innate immune stimulation in the absence of active infection." (PMID 40869330, 2025).
neurodegenerative disease (4 papers, 2022 to 2023). A disorder of the central nervous system characterized by gradual and progressive loss of neural tissue and neurologic function. "Decreased expression of pro-inflammatory genes, which are associated with neurodegenerative disease or astrocyte and microglia phenotypes Cd40, C1qB, Cd68, Cd45, Aqp-4, Il1α, Fkbp5, Ggta1, Cd16, H2-T23, and Serping1, was observed following C-32:6 treatment and C1qC, Tspo, and Gbp2 with FFA C-34:6." (PMID 37740008, 2023). "Finally, several proteins that are associated with neurodegenerative diseases were upregulated either during isolation (Pfn4, C1qb, Bag5 and Sv2c) or following regrouping (oxidative phosphorylation-associated genes such as Ndufc2)." (PMID 34650208, 2022).
neurological diseases (2 papers, 2022). "The proteins encoded by C1QA and C1QB belong to the C1q family, whose members are the first components of the complement pathway and are involved in complement system regulation and play crucial roles in neurological disorders." (PMID 35221911, 2022). "The serum complement subcomponent C1q's C-chain or B-chain polypeptides, which are crucial in the regulation of the complement system and have significant effects on neurological diseases, are encoded by the genes C1QA or C1QB." (PMID 36703641, 2022).
C1QB also shares sentences with these, for which no sentence is quoted: lung adenocarcinoma (3 papers); adenocarcinoma (2); glomerulonephritis (2); pertussis (2); prostate carcinoma (2); sarcoidosis (2); adenosquamous carcinoma (1); amnesia (1); Anxiety (1); autoimmune disease (1); B-cell lymphoma (1); bladder cancer (1); brain tumor (1); clear cell renal cell carcinoma (1); cognitive decline (1); coronary artery disease (1); dysplastic nevi (1); endometriosis (1); endothelial dysfunction (1); Erythema (1); esophageal cancer (1); glioblastoma (1); hepatocellular carcinoma (1); Huntington disease (1); hyperopia (1); infectious disease (1); ischemia (1); kidney diseases (1); leukemia (1); liver cirrhosis (1).
A further 30 diseases each share a sentence with C1QB in 1 paper.